MTOR (mechanistic target of rapamycin kinase)
Diseases named in the same sentence as MTOR in open-access papers (continued):
Sharing a sentence is not in itself a finding about the gene and the disease.
breast cancer (continued). "However, none of the studies have, so for, reported the mechanism of anticancer action of Ajwa dates pulp extract by modulation of Bcl-2 family proteins and downregulation of AKT/mTOR signaling pathway in breast carcinoma MDA-MB-231 cells." (PMID 33990623, 2021). "The current study concluded that the novel ruthenium-fluvastatin complex is capable of downregulating SNCG expression associated with breast carcinoma cell line regulation by inhibiting cell proliferation and inducing apoptosis by triggering the cascade of PI3K/Akt/mTOR/VEGF/MMP9." (PMID 34221232, 2021). "Our findings suggest that mTOR signaling pathway could be responsible for its preventive effect in the breast cancer." (PMID 33163084, 2020). "Therefore, the introduction of mTORC1/C2 or dual inhibitors (acting on different levels of the mTOR pathway) should be considered in breast cancer therapy." (PMID 32899149, 2020). "Moreover, UCA1 has been implicated in hormone therapy resistance in breast cancer cells as it sponges miR-18a, leading to HIF1α activation or inhibition of mTOR signaling, suggesting its multiple functions in breast cancer metabolism." (PMID 33123488, 2020). "With respect to increased LDs in response to exogenous supplementation with oleic acid, this cellular response appears to be similar to that with fatty acid synthase (FAS) inhibitors along with mTOR inhibitors which results in synergistic toxicity in breast cancer cells." (PMID 32492043, 2020). "In addition, a preclinical study assessing the effects of palbociclib and the mTOR inhibitor sapanisertib, showed that their combination synergistically inhibited breast cancer cell proliferation." (PMID 32351542, 2020). "Activated PI3K/Akt/mTOR pathway have been documented in breast cancers." (PMID 32606352, 2020). "In this study, we found that eEF-2K, which is overexpressed in cancer cells and is required for survival of stressed cells, was involved in the negative-feedback activation of Akt and cytoprotective autophagy induction in breast cancer cells in response to mTOR inhibitors." (PMID 33144562, 2020). "The PI3K/AKT/mTOR pathway has been found to be dysregulated almost in all human cancers, such as breast cancer, colorectal cancer, and hematologic malignancies, which emphasizes the value of targeting this pathway as a potential therapeutic direction in the treatment of cancer." (PMID 33123313, 2020). "Previous studies have shown that activated PI3K/mTOR signaling may be playing a role in resistance to CDK4/6-based therapies in ER+ breast cancer." (PMID 32795346, 2020). "In preclinical studies, combination treatment with a nucleotide-derivative AKT inhibitor significantly enhanced the antiproliferative activity of an anti-HER2 antibody in breast cancer xenograft models, while combination treatment with a rapamycin-derivative mTOR inhibitor did not45." (PMID 33303839, 2020). "In addition, previous studies have shown a significant inhibition of mitochondrial complex I, activation of AMP-activated protein kinase (AMPK) and inhibition of mTOR with metformin treatment of breast cancer cells." (PMID 32012648, 2020). "Collectively, these results showed T-DM1 could inhibit Akt/mTOR signaling pathway and Akt/mTOR pathway inactivation was associated with T-DM1-triggered autophagy in both HER2-positive breast cancer cells." (PMID 32495214, 2020). "In addition, it was previously reported that PI3K/AKT/mTOR signaling pathway activation promotes cell cycle progression in CDK4/6 inhibitor resistant breast cancer cells through increased CDK2 and cyclin E." (PMID 32899250, 2020). "mTOR is involved in PI3K/AKT signaling pathways, being associated with cell survival, proliferation, metabolism, and angiogenesis, and being abnormally activated in breast cancer." (PMID 33375317, 2020).
breast cancer (continued). "The translation of a subset of the mRNA isoforms of NANOG, SNAIL, and NODAL promoted breast cancer cell plasticity in response to hypoxia, mTOR inhibition and chemotherapy by allowing efficient translation and escape from stress-induced translational repression." (PMID 32427827, 2020). "Therefore, DHW-208 was an effective and hypotoxic compound and inhibited the growth of human breast cancer cells via the PI3K/AKT/mTOR-signaling pathway." (PMID 32606352, 2020). "The hyperactivation of Akt and consequently mTOR may facilitate the resistance that some patients with breast cancer have to endocrine therapies; in these patients, an inverse correlation was established between Akt activation and a partial treatment response." (PMID 32211045, 2020). "In addition, the coumarin-derivate compound 5-methoxypsoralen (Bergapten) upregulated PTEN and p38 MAPK/NF-Y pathways and inactivated Akt/mTOR pathway resulting in autophagy and the inhibition of the survival of breast cancer cells (MCF-7 and ZR-75)." (PMID 32927836, 2020). "Furthermore, the Akt/mTOR/p70S6K pathway was significantly inhibited by carbon ion radiation in both breast cancer cell lines." (PMID 32239160, 2020). "Therapies that inhibit mTOR prolong progression-free survival and have been approved for use in multiple cancers, including renal cell carcinoma, neuroendocrine tumors, and advanced breast cancer, with trials ongoing in other malignancies." (PMID 32012988, 2020). "Furthermore, BEZ235 a dual inhibitor of PI3K and mTOR significantly decreased the adipocyte-mediated the proliferation and migration of breast cancer cells." (PMID 32201525, 2020). "In addition, we previously reported that SJWE regulated proliferation and apoptosis in MCF-7 breast cancer cells by inhibiting the AMPK/mTOR and Bcl-2 family pathways." (PMID 33080824, 2020). "Based on the finding that SGLT1 activated PI3K/Akt/mTOR signaling in HER2+ breast cancer, we tested whether SGLT1, stabilized by HER2, promoted cell growth and proliferation." (PMID 32377271, 2020). "One of the mechanisms through which leptin causes breast cancer progression is the regulation of breast cancer stem cell (CSC) activity by modulating the many signalling pathways (i.e., Notch, Wnt, mTOR, STAT3, HER2/Erb, and IGF pathways) and transcription factors (i.e., HIF-1 and NFκB)." (PMID 32033341, 2020). "Given the role of BCSC plasticity in therapy resistance and metastasis, the administration of ISRIB may improve outcomes in breast cancer patients treated with mTOR inhibitors or chemotherapy." (PMID 32427827, 2020). "Activation of the PI3K/Akt/mTOR signaling pathway plays a significant role in controlling cell growth, proliferation and metastasis, and has been identified as an important potential therapeutic target in breast cancer." (PMID 32669950, 2020). "Furthermore, it is consistent with the findings that MNX1-AS1 upregulated proliferation and invasion in breast cancer by activating AKT/mTOR pathway which was overlapped with JAK/Stat3 signaling pathway." (PMID 32754442, 2020). "Mammalian target of rapamycin (mTOR) inhibitors may be used in combination with exemestane in selected postmenopausal breast cancer patients with metastatic disease and have shown improved progression free survival compared with exemestane alone." (PMID 32979150, 2020). "In addition, metformin has been shown to inhibit PI3K/AKT/mTOR signaling in lung cancer, breast cancer, pancreatic cancer, and hepatic cancer." (PMID 32825834, 2020). "As RAS may activate PI3K, our findings might lend evidence to explain how PI3K/AKT/mTOR signalling is hyper‐activated by DEPDC1 in breast cancer cells, which was reported in a previous study." (PMID 33021072, 2020). "Therefore, our results suggest that the anti-proliferation activity of DHW-208 in breast cancer cells is associated with G0/G1 cell cycle arrest, which is achieved by regulating the protein expression levels in PI3K/AKT/mTOR." (PMID 32606352, 2020).
breast cancer (continued). "ER+ breast cancer frequently shows a hyperactivation of the mTOR pathway." (PMID 32351542, 2020). "Recent reports have demonstrated that the PI3K/Akt/mTOR pathway is frequently altered in human breast cancer, and both genetic and biochemical data suggest that aberrant activation of the PI3K/Akt/mTOR pathway contributes to breast cancer development and tumourigenesis." (PMID 32239160, 2020). "These emerging pieces of evidence suggest that levobupivacaine may inhibit proliferation and promote apoptosis by suppressing PI3K/Akt/mTOR signalling pathway, which demonstrated an anti-tumour effect on breast cancer cells in this study." (PMID 32807213, 2020). "We searched PubMed between Jan 1, 2009, and July 31, 2019, to identify publications directly relevant to the FAKTION clinical setting using the search terms “AKT” or “PI3K” or “mTOR” and “oestrogen receptor” and “breast cancer” and “metastatic” and “inhibitor” or “inhibition”." (PMID 32035020, 2020). "Rapamycin is an inhibitor of mTOR that is used as an immunosuppressant in breast cancer therapy." (PMID 32335998, 2020). "The mTOR inhibitor, which is conventionally used as a therapeutic agent in various solid cancers, including breast cancer and renal cell carcinoma, may serve as a substitute for the Mig-6 inhibitor." (PMID 32552717, 2020). "We next wanted to know whether mitoxantrone can augment mTOR inhibitor-induced cytotoxicity in breast cancer cells by inhibiting eEF-2K." (PMID 33144562, 2020). "Therefore, inhibition of the PI3K/AKT/mTOR signaling pathway should be of great priority to overcome therapeutic challenges in HR+ breast cancer." (PMID 32461963, 2020). "The PI3K/Akt/mTOR pathway is altered more frequently than any other pathway in breast cancer." (PMID 32438621, 2020). "Dysregulation of PI3K/AKT/mTOR-signaling is a regulator of aerobic glycolysis and provides scientific rational for controlling insulin-activation of PI3K/AKT/mTOR in both women with breast cancer and at-risk women." (PMID 32153503, 2020). "The PI3K/Akt/mTOR pathway is related to various biological processes in breast cancer, such as tumorigenesis, cellular transformation, tumor progression, and drug resistance (Guerrero-Zotano, Mayer & Arteaga, 2016)." (PMID 33150070, 2020). "In particular, PI3K/AKT/mTOR is the most frequently altered pathway in HR+ breast cancer." (PMID 32461963, 2020). "Acquiring the resistance to mTOR inhibitors (most commonly rapamycin and its derivates) was detected in various tumours' models in vitro as well as in vivo in patients suffering from such conditions as i.a. breast cancers, gliomas 3,4,31." (PMID 33173419, 2020). "Casticin induced cytotoxicity and reduced cell proliferation by blocking the phosphorylation of Akt (Ser473) and mTOR (Ser2448) proteins, indicating the involvement of Akt/mTOR signaling pathway, in human breast cancer MCF-7, gastric cancer SNU16, and myeloma RPMI 8226 cells." (PMID 31952105, 2020). "In addition, we found that NH125, a well-known eEF-2K inhibitor, also further augmented mTOR inhibitor-induced cytotoxicity in breast cancer cells." (PMID 33144562, 2020). "BELLE-3 was a randomized, double-blind, placebo-controlled, phase III study comparing Buparlisib plus fulvestrant to placebo plus fulvestrant in postmenopausal women with ER-Positive, HER2-negative advanced breast cancer progressing on or after mTOR inhibition." (PMID 32210163, 2020). "Here, we also demonstrated that AA can inhibit PI3K/AKT/mTOR activation, leading to inhibited proliferation, inhibited migration, inhibited invasion, enhanced apoptosis, and arrest of G2M/S phase cell cycle in breast cancer cells as same as BEZ235 (inhibitor of PI3K/mTOR)." (PMID 32976685, 2020). "Regardless of alterations in the PI3K/AKT/mTOR pathway, a further determination of underlying gene alterations should be of obligation to develop the novel therapeutic strategy in breast cancer." (PMID 32461963, 2020).
breast cancer (continued). "The authors propose that the osteoblast–breast cancer cell interaction might be regulated via E- and N-cadherins, consequently resulting in an enhancement of mammalian target of rapamycin (mTOR) activity in the cancer cells." (PMID 32092997, 2020). "Hyperactive mTOR signalling is known to occur in different cancers, including breast carcinomas, and additionally, it may contribute to metabolic plasticity and tumour progression." (PMID 32899149, 2020). "Mammalian target of rapamycin (mTOR) hyperactivity may contribute to this metabolic plasticity and progression in breast carcinomas." (PMID 32899149, 2020). "FBXW7 and PTEN works together to inhibit breast cancer progression by suppressing mTOR." (PMID 31064356, 2019). "Current study also have reported that several lncRNAs can affect PI3K‐Akt‐mTOR signaling pathway key proteins expression such as breast cancer, cervical cancer, and non‐small cell lung cancer, but similar studies about LOC101928316 for GC have not been reported." (PMID 31207155, 2019). "Previous case reports have shown the promising antitumor activity of everolimus in solid tumors containing molecular aberrations in PI3K/ATK/mTOR pathway, however, whether it is effective in patients with breast cancer remains unknown." (PMID 31385461, 2019). "In addition, P. yezoensis peptides also protected against breast cancer by activating the mammalian target of rapamycin (mTOR) signaling pathway in MCF-7 cells." (PMID 31083497, 2019). "In addition, the PI3K/AKT/mTOR signaling pathway acts a crucial role in multiple cellular processes that contribute to the malignant phenotype of breast cancer." (PMID 31032225, 2019). "There might be a pathway of ROS-mediated PI3K/AKT/mTOR activation to breast cancer that is in part controlled by DNA demethylation in the promoter region of the MTOR gene." (PMID 30678711, 2019). "We report here that mTOR-dependent MCL1 translation rapidly drives Mcl-1 upregulation in ER+ breast cancer cells treated with ABT-263, or with BH3 mimetics that target Bcl-2 alone (ABT-199) or Bcl-xL alone (A1155463), consistent with the well-established oncogenic role of mTOR in ER+ breast cancers." (PMID 31595181, 2019). "Therefore, we sought to examine the therapeutic effects of mTOR inhibition in relation to BRCA1 expression in breast cancer cell lines." (PMID 31771139, 2019). "In summary, our study shows that glutamine pathway is altered in endocrine resistant breast cancer cell models and co-targeting enhanced glutamine requirement with mTOR may be useful in impeding growth of this advanced stage of ER+ breast cancer." (PMID 31428575, 2019). "However, irradiation with a single dose of 5 Gy promoted OXPHOS via mTOR-mediated enzymatic inhibition of hexokinase II in tumor cell lines (breast cancer MCF-7 cells, colon cancer HCT116 cells, and glioblastoma U87 cells) associated with the Warburg effect." (PMID 31929797, 2019). "Moreover, mTOR expression is correlated with poor prognosis in breast cancer, and phosphor-mTOR was more common in TNBC." (PMID 30754640, 2019). "It was reported that frankincense and geranium essential oils could suppress tumor progression through the regulation of the AMPK/mTOR pathway in breast cancer." (PMID 31801196, 2019). "Furthermore, quercetin also induced Akt-mTOR mediated autophagy in breast cancer cells where it reduced the migration and metastasis of cells through MMP-2, MMP-9, and VEGF inhibition." (PMID 31064104, 2019). "Inhibition of mTOR restores tamoxifen resistance in breast cancer cells." (PMID 31277692, 2019).
breast cancer (continued). "Studies have affirmed that an oncogene FAM83D (family with sequence similarity 83, member D) present on chromosome 20q has a significant role in breast cancer development by downregulating FBXW7 resulting in amplification of its oncogenic substrates such as mTOR." (PMID 30791487, 2019). "mTOR/eIF4E axis is found to contribute to breast cancer maintenance and progression." (PMID 29769411, 2019). "Several Phase II clinical trials have evaluated use of mTOR inhibitors for ER+ breast cancer." (PMID 31122207, 2019). "Thus, our results confirm that activation of the Akt/mTOR pathway contributes to tamoxifen resistance in breast cancer, but also reveal a novel mechanism for regulation of the Akt/mTOR signaling pathway involving the SALL2–PTEN axis." (PMID 31657150, 2019). "For instance, everolimus is an mTOR inhibitor and was approved for breast cancer treatment." (PMID 30678711, 2019). "Moreover, the activation of PTEN/mTOR/STAT3 pathway in breast cancer cells is required for the viability and maintenance of a subpopulation enriched in CSCs, defined as the side population (SP)." (PMID 31366089, 2019). "However, it is reasonable that these aspects pertain to protective factors considering the corresponding targeted medicine, such as the CDK and mTOR inhibitors that are currently applied in breast cancer patient treatments." (PMID 30778902, 2019). "Moreover, an inverse association was found between DNA methylation at cg08862778 (MTOR gene) and breast cancer." (PMID 30678711, 2019). "EGFR is an upstream component of the PI3K/mTOR signaling pathway in human neoplasms and is overexpressed in numerous malignant carcinomas (such as breast cancer, gastrointestinal adenocarcinoma, colorectal cancer, and lung cancer) and indicates poor prognosis of cancer." (PMID 30863440, 2019). "For paclitaxel resistance, the following miRNAs are relevant, miR-17-5P for the target PTEN in ovarian cancer, miR-30c for the targets VIM, IL-11 in breast cancer, miR-125b for Sema4C and Bak1 in breast cancer, and miR-100 for mTOR, miR-145 for P-gp in ovarian cancer, and miR-181a for PTEN in NSCLC." (PMID 35582143, 2019). "We considered that SPAG5 was correlated with mTOR signaling pathway activity during breast cancer treatment, and the cross-talk between the estrogen receptor and mTOR signaling pathway, the most well-known mechanism of endocrine resistance, led to poor prognosis of patients." (PMID 31690268, 2019). "Therefore, our finding adds evidence to a pathway of ROS-mediated PI3K/AKT/mTOR activation to breast cancer development." (PMID 30678711, 2019). "Furthermore, ipatasertib (GDC‐0068), an Akt inhibitor currently used in clinical breast cancer therapy, was used to examine the crucial effect of Akt/mTOR signaling pathway on SALL2 downregulation‐induced tumorigenicity of ER+ breast cancer cells." (PMID 31657150, 2019). "PI3K/AKT/mTOR is one of the most commonly identified oncogenic-driver pathways in breast cancer." (PMID 31320990, 2019). "Wedelolactone inhibits breast cancer-induced osteoclastogenesis by inhibiting AKT/mTOR signalling." (PMID 30609679, 2019). "Here we have demonstrated that treatment of breast cancer and colorectal cancer cells with a pan-mTOR inhibitor synergistically increases the growth-inhibitory action of the Akt-inhibitor MK2206 which corresponded with changes in the incorporation of radiolabelled choline." (PMID 30056610, 2019). "Thus, there is a rationale to treat patients with a combination of chemotherapeutics that induce DNA damage and mTOR inhibitors, like rapamycin, due to additive cytotoxic effects in breast carcinoma cell lines." (PMID 31288154, 2019). "In our present study, we investigated whether 20(S)-PPD may induce apoptosis in human breast cancer MCF-7 cells by targeting the PI3K/AKT/mTOR signaling pathway." (PMID 29614812, 2018).